GPX4 (glutathione peroxidase 4)
Diseases named in the same sentence as GPX4 in open-access papers (continued):
Sharing a sentence is not in itself a finding about the gene and the disease.
tumor (continued). "Additionally, tumor cells with mutations in isocitrate dehydrogenase 1 (IDH1) undergo metabolic changes, leading to elevated levels of 2-hydroxyglutarate (2-HG), which inhibits the activity of GPX4, promoting the accumulation of intracellular ROS." (PMID 40709182, 2025). "However, tumor cells overexpress GPX4 (an antioxidant enzyme) to regulate ferroptosis." (PMID 40746825, 2025). "Metadherin plays an important role in inducing epithelial-mesenchymal transformation (EMT), proliferation, and invasion of tumor cells, promoting treatment resistance and mesenchymal hypercytosis while increasing the vulnerability of tumor cells to ferroptosis inducers, especially GPX-4 inhibitors." (PMID 40169575, 2025). "The potential of ferroptosis inducers (e.g., GPX4 inhibitors or system xc− blockers) is being explored in preclinical models of breast cancer, lung cancer, and melanoma, highlighting its broad applicability in modulating tumor vulnerability and enhancing immune responses." (PMID 41301464, 2025). "In addition, tumor cells exhibit metabolic heterogeneity, with some leveraging oxidative stress for survival and proliferation, while others over-activate endogenous antioxidant mechanisms, such as GPX4 or NRF2, to resist external antioxidant treatments." (PMID 40563308, 2025). "Indeed, tumor cells may significantly enhance their oxidative stress defense ability by upregulating the SLC7A11/GSH/GPX4 axis, achieving drug resistance and survival to ferroptosis." (PMID 40229247, 2025). "Notably, drug‐resistant tumor cells exhibit heightened sensitivity to GPX4‐mediated ferroptosis." (PMID 40919133, 2025). "Further studies showed that the degradation of GPX4 induced by terpenoids is tissue selective, and the degradation efficiency in tumor cells is significantly higher than that in normal cells, which may be related to the abnormal active protein degradation system in tumor cells." (PMID 40559667, 2025). "Finally, we assessed the levels of GPX4, xCT, and Ferritin in tumor tissue." (PMID 40136455, 2025). "However, there is a therapeutic difference between GPX4 inhibitors and other tumor treatments." (PMID 40969276, 2025). "Moreover, inhibition of GPX-4 promotes the ferroptosis in tumor cells." (PMID 40191728, 2025). "In lung cancer, CTRP6 promotes tumor proliferation and metastasis, while its knockdown induces ferroptosis via the xCT/GPX4 axis through SOCS2 ubiquitination and degradation, suggesting that targeting CTRP6 could sensitize tumors to ferroptosis-based therapies." (PMID 41228203, 2025). "Therefore, the development of safer, tumor-selective GPX4 inhibitors or nanoparticle-based delivery systems for RSL3, in conjunction with existing therapies, may be necessary to effectively harness ferroptosis in therapy-resistant HNC." (PMID 41185600, 2025). "Thus, GPX4 is a major regulator of tumor cell death due to ferroptosis." (PMID 41287824, 2025). "However, PDT may also induce DNA damage and repair responses, upregulating GPX4 expression and degrading ROS, thus inducing resistance in tumor cells to the treatment." (PMID 40191731, 2025). "Notably, pharmacological inhibition of lipid peroxidation through targeting GPX4 or ACSL4 has been shown to overcome tumor resistance to immunotherapy and improve clinical outcomes, thereby presenting a promising strategy for developing combinatorial treatment regimens." (PMID 40563367, 2025). "However, GPX4 deletion in Tregs can activate ferroptosis, promote IL-1β production, and enhance Th17 cell responses, thereby enhancing antitumor immunity and inhibiting tumor growth." (PMID 40760119, 2025).
tumor (continued). "Therefore, the typical GPX4 regulatory pathway plays an important role in tumor biology." (PMID 38469234, 2024). "Interestingly, AIFM2 and GPX4 have been determined as vital regulators of tumor cell ferroptosis." (PMID 38244593, 2024). "GPX4 may exert anti-tumour activity and reflect an improved differentiation phenotype in BC." (PMID 38528461, 2024). "Therefore, targeting Treg cell GPX4 or promoting ferroptosis in Treg cells could be key to improving tumor immunotolerance." (PMID 39726588, 2024). "Moreover, the PI3K/AKT pathway mediates GPX4 function and regulates ferroptosis in tumour cells." (PMID 39881871, 2024). "Additionally, the release of exosomes containing damaged DNA has been found to induce DCs maturation through the cGAMP-STING-TBK1 pathway, while the secretion of IFN-β activates CD8+T cells, resulting in the release of IFN-γ and subsequent inhibition of GSH and GPX4 expression in tumor cells." (PMID 38853203, 2024). "Consequently, focusing on manipulating GPX4 could offer a potential strategy in enhancing tumor therapy, particularly in overcoming sorafenib resistance." (PMID 38745179, 2024). "Therefore, GPx4 overexpression is capable of impairing GBM tumor growth and cell viability." (PMID 39709480, 2024). "Moreover, GPX4 may counteract cell death (ferroptosis) in proliferating tumor cells, a fate that otherwise would be triggered by the oxidative stress associated with excess ROS." (PMID 39666242, 2024). "Furthermore, immunostaining of CYP4F3, Ki67, NRF2, and GPX4 were performed on the tumor tissues." (PMID 39106550, 2024). "Specific deletion of Gpx4 in Tregs impairs their survival in tumors, increases infiltration of T cells into tumors, and enhances antitumor immune responses, indicating that Gpx4 maintains the survival and immunosuppressive functions of Tregs to promote tumor immune evasion." (PMID 38965216, 2024). "Furthermore, inhibiting CKS2 promoted tumor ferroptosis by downregulating GPX4 expression." (PMID 39548421, 2024). "In addition, Gpx4 can suppress anti-tumor immunity by promoting Treg cell survival in the tumor." (PMID 39192972, 2024). "In addition, a low HDS may activate the immune microenvironment by inhibiting the MIF signaling pathway in the TME and regulating GPX4 expression in tumor cells." (PMID 37649598, 2023). "Furthermore, GPX4 deficiency, rather than intra-tumor Treg cell apoptosis, enhances antitumor immune function and inhibits tumor growth by inducing ferroptosis." (PMID 37213276, 2023). "In addition, in primary GC, GPX4-Mpr1/Pad1 N-terminal domain-containing protein (MPND) fusion gene can facilitate tumor growth and progression, which suggests that GPX4 may be a potential molecular marker for early diagnosis and prognosis of GC." (PMID 37768308, 2023). "Additionally, in clinical treatment, GPX4 upregulation promotes ferroptosis of tumor cells and may fail to achieve the desired effect because of the activation of the compensatory mechanism of the FSP1 system." (PMID 37564215, 2023). "Additionally, the χc−/GSH/GPX4 axis contributes to the regulation of tumor chemoresistance." (PMID 37149513, 2023). "In addition, combined use of ferroptosis inducers could inhibit the growth of tumor cells with high GPX4 expression, implying a new approach for cancer treatment." (PMID 35155264, 2022). "Therefore, the inhibition of Systeam Xc-, the blocking of GSH synthesis and the inactivation of GPX4 may serve as an important target for inducing ferroptosis in tumor cells." (PMID 36387286, 2022).
tumor (continued). "Furthermore, we found the classic ferroptosis suppressor gene GPX4 showed upregulated expression in TTs, implying inducing ferroptosis through regulation of GPX4 for tumor therapy might be more effective in TTs than in PTs in ccRCC patients." (PMID 35361264, 2022). "Furthermore, lovastatin and combined treatment inhibited GPX4 expression in mouse tumor tissues." (PMID 35943796, 2022). "Furthermore, glutathione depletion inactivated GPX4, which inhibits lipid peroxides, and enhanced ferroptosis, demonstrating the potential to overcome drug resistance by inducing sensitized apoptosis and collaborative ferroptosis of tumor cells." (PMID 35847022, 2022). "In addition, inhibition of SLC7A11 or GPX4 can increase the radiosensitivity of tumor cells to IR." (PMID 36317423, 2022). "Moreover, the expressions of CASP6, GPX4, GSDMC, and NOD2 could increase the susceptibility of tumor cells to paclitaxel, 5-fluorouracil, dasatinib, and gefitinib." (PMID 35368686, 2022). "Indeed, high expression of GPX4 in NB tumor tissues predicts poor prognosis." (PMID 34011924, 2021). "The nano-carrier could be dissolved in the weak acidic microenvironment to release ART and Fe(II), which is further caused a high level of intracellular ROS and MDA, accompanied with decreasing of GSH and GPX4, leading to potent tumor growth inhibition and anticancer efficacy in vitro and in vivo." (PMID 33620584, 2021). "FANCD2 may prevent erastin-induced GPX4 degradation and reduce tumour sensitivity to ferroptosis." (PMID 34095228, 2021). "In addition, intratumoral injection of ML162 also prevented tumor growth alone or combined with sorafenib, suggesting that intratumoral administration could be a feasible delivery approach for direct GPx4 inhibitors." (PMID 31527591, 2019). "Ginsenoside Rh4 induces ferroptosis by inhibiting the KEAP1/NRF2/HO-1 pathway and remodeling the gut microbiota to increase butyrate levels, which synergistically enhance tumor cell ferroptosis sensitivity through ATF3 activation and suppression of GPX4." (PMID 41898564, 2026). "Overexpressing GPX4 or FSP1 enhances the resistance of CD8+ T cells to ferroptosis, thereby exerting their anti‐tumor immune function." (PMID 41560416, 2026). "However, parental cells are also killed by combining FSP1 and GPX4 inhibition, although to a lesser degree than persister cells, suggesting that this combination treatment may be useful to simultaneously induce ferroptosis in both tumor cell populations." (PMID 41481741, 2026). "OTUB1 suppresses ferroptosis and maintains tumor cell survival by deubiquitinating and stabilizing key proteins like SLC7A11, GPX4, and p62." (PMID 42086528, 2026). "Treg cells with GPX4 knocked out enhance the TH17 cell response by secreting IL‐1β, promoting the body's anti‐tumor immune function." (PMID 41560416, 2026). "Mitomet differentially increased mROS in LKB1 mutant tumor spheres, thereby suppressing levels of MMP, ATP synthesis, GPX4, and phospho-ACC, which then culminated in increased lipid peroxidation and cell death." (PMID 42138621, 2026). "In vivo, combination dabrafenib and ferroptosis induction (by targeting GPX4 using C18, and system Xc− with IKE) significantly inhibited tumor growth in an orthotopic ATC mouse model." (PMID 41501927, 2026).
tumor (continued). "GC cells are typically resistant to ferroptosis due to increased expression of ferritin and glutathione peroxidase 4 (GPX4), which promotes tumor growth and contributes to chemoresistance." (PMID 41526983, 2026). "In this study, we reanalyzed publicly available single-cell RNA sequence data of HCC tumors and identified a distinct tumor cell cluster characterized by reduced SELENOP expression, enhanced GPX4 and TXNRD1 expression, and activation of NRF2 signaling." (PMID 40818321, 2025). "At the same time, some marine steroids can up-regulate the expression of GPX4, FSP1, and PPARα by activating FXR, forming a multi-layered lipid peroxidation defense network, which provides a potential target for reversing tumor ferroptosis resistance." (PMID 40559667, 2025). "LAR tumours had higher rates of lipid peroxidation and were shown to upregulate the SLC7A11/GSH/GPX4 axis to escape ferroptosis." (PMID 40136651, 2025). "This system reduces cysteine transport into cells during the body’s immune response, leading to decreased expression of glutathione (GSH) and glutathione peroxidase 4 (GPX4), thereby inducing ferroptosis in tumor cells and impeding tumor growth." (PMID 39820341, 2025). "Intriguingly, dynamic equilibrium exists between mGPX4 and DHODH pathways: tumor cells counteract LPO induced by DHODH inhibition through mGPX4 upregulation, whereas cytosolic GPX4 lacks such compensatory capacity." (PMID 40919133, 2025). "For instance, in gastric cancer, lipid peroxides trigger ferroptosis via the GPX4/SREBP-1α pathway, suppressing tumor cell growth." (PMID 40636119, 2025). "Subsequent IHC analysis of GPX4, FTH1 and TFRC expression in subcutaneous tumours from DLBCL xenograft model yielded similarly results." (PMID 40038872, 2025). "Future studies must prioritize tumor-specific delivery systems and the use of biomarkers such as ACSL4 and GPX4 for patient stratification to translate these findings into clinical practice." (PMID 41268067, 2025). "In contrast, Tregs show limited lipid peroxidation compared to tumor-specific CD8+ T cells and induction of GPX4 expression upon TCR activation protects them from ferroptosis." (PMID 40760119, 2025). "Both in vitro and in vivo experiments demonstrated that Mn-S1N3 effectively induces irreversible tumor ferroptosis through lipid peroxidation (LPO) and glutathione peroxidase 4 (GPX4) inactivation." (PMID 41215762, 2025). "OSCC cells exhibit heightened reliance on anti-ferroptotic defenses such as GPX4, SLC7A11, FSP1, and Nrf2, and disrupting these pathways suppresses tumor growth and restores sensitivity to chemotherapy, radiotherapy, and immunotherapy." (PMID 41227330, 2025). "Western blot analysis showed that sh-circASH1L accelerated the cisplatin-induced reduction of GPX4 and SLC7A11 expression, as well as the downregulation of CDCA7 and RRM2 in tumor tissues." (PMID 40630134, 2025). "IHC staining and WB in xenograft tumor tissues revealed lower NRF2 and GPX4 expressions in the CLDN6 overexpression and sorafenib-treated CLDN6 overexpression groups compared to controls." (PMID 39984471, 2025). "• It catalyzes the production of O2 from H2O2 to alleviate tumor hypoxia, while decreasing the expression of GSH and GPX4, thereby enhancing SDT and producing better antitumor effects in H22- and 4T1-loaded mice." (PMID 41426324, 2025). "This inhibition leads to the downregulation of NRF2 downstream targets Glutathione Peroxidase 4 (GPX4) and SLC7A11, resulting in the induction of ferroptosis in tumor cells." (PMID 40258841, 2025). "As intercellular communication carriers, exosomes can transport signaling molecules related to ferroptosis (such as miRNAs, GPX4, ACSL4, iron metabolites, etc.), reflecting tumor progression, prognosis, and treatment sensitivity." (PMID 40328736, 2025).
tumor (continued). "Multiple drug classes have entered clinical investigation, including system Xc− inhibitors and GPX4 inhibitors, which promote LPO accumulation in tumor cells by blocking cystine uptake or inhibiting GPX activity." (PMID 40919133, 2025). "By orchestrating the expression of detoxifying enzymes (e.g., GPX4 and HO-1), cystine transporters (e.g., SLC7A11), iron regulators, and immune modulators (e.g., PD-L1), Nrf2 enables tumor cells to adapt to ferroptotic stress." (PMID 40867889, 2025). "For example, a hypoxic tumor micro-environment can mediate tumor cell ferroptosis resistance by activating HIF1α and upregulating various anti-ferroptosis molecules such as SLC7A11, GPX4, TFRC and FTH115-17." (PMID 41049011, 2025). "Concordantly, tumours from the LDHA group exhibited up‐regulated protein levels of Pan‐Kla, H3K18la, IGF2BP2, Nrf2 and GPX4." (PMID 41399129, 2025). "EIF2S1 controls GPX4 and SLC7A11 expression to protect tumor cells from ferroptosis, thus promoting tumor growth." (PMID 40302793, 2025). "Curcumin, neferine, and TDH have all been demonstrated to reduce GPX4 or SLC7A11 activity, increase ROS, and suppress ATC tumor growth in vivo." (PMID 41294853, 2025). "In non-small cell lung cancer (NSCLC), PRKAA2 enhances tumor growth and suppresses ferroptosis via the SLC7A11/GSH/GPX4 pathway." (PMID 40575157, 2025). "To confirm the clinical relevance of GPX4 in PCa, we performed an immunohistochemistry (IHC) analysis of a tissue microarray (TMA) composed of tumor tissue cores from patients affected by PCa at different stages." (PMID 40569831, 2025). "GPX4, PCBP1, and PCBP2 protein levels were reduced in tumor tissues in a dose-dependent manner, which was consistent with the results of the in vitro experiments." (PMID 40619432, 2025). "This limits the activity of both GPX4 and FSP1, sensitizing cancer cells to ferroptosis in several tumor types." (PMID 41227330, 2025). "Tumor-localized CatB activates the PROTAC for sustained DHODH degradation, while NIR-triggered BP release inhibits GPX4 via selenocysteine binding, synergistically inducing ferroptosis through dual-pathway targeting." (PMID 40871058, 2025). "Conversely, other evidence shows GPX4 inhibitors can trigger CTL ferroptosis in vitro, impairing their anti-tumor activity and promoting immune escape." (PMID 41035634, 2025). "Fe2+/Fe3+ and DOX synergistically triggered tumor ferroptosis through LPO and GPX4 suppression, releasing DAMPs (e.g., mtDNA, HMGB1) to activate ICD." (PMID 40846966, 2025). "The objective of this study is to investigate the role of GPX4 in NSCLC, with a particular focus on its molecular mechanisms in tumor advancement and resistance to drugs." (PMID 40191731, 2025). "We clarified that UA exhibits obvious anti-tumor capacity in CRC cells by promoting ferroptosis via modulation of system xc- and miR-214-3p/Stat3/GPX4 axis, which eventually depletes glutathione (GSH), inactivates GPX4 and decreases GPX4 expression levels." (PMID 41341590, 2025). "Immunohistochemical analysis revealed GPX4 suppression and DLAT aggregation in tumors treated with E. coli@Cu2O plus 1064 nm laser, achieving complete tumor eradication in vivo." (PMID 40892295, 2025). "As shown in the results, the delay in tumor growth was considerably more pronounced in the combination group than in the single–axitinib–treated group, with reduced expression of IFI6 and GPX4." (PMID 39988631, 2025). "Researchers found that valtrate (Val) dramatically reduces tumor size and weight in xenograft tumor models by raising cleaved caspase-3 expression and lowering SLC7A11 and GPX4 expression." (PMID 40191731, 2025).